BGN (biglycan)
Diseases named in the same sentence as BGN in open-access papers (continued):
Sharing a sentence is not in itself a finding about the gene and the disease.
osteoarthritis (9 papers, 2011 to 2025). A noninflammatory degenerative joint disease occurring chiefly in older persons, characterized by degeneration of the articular cartilage, hypertrophy of bone at the margins and changes in the synovial membrane. "Hemizygous missense variants in the X-linked BGN gene, encoding the extracellular matrix protein biglycan, cause spondyloepimetaphyseal dysplasia (SEMD, biglycan type), which is clinically characterized by short stature, brachydactyly and osteoarthritis." (PMID 36640472, 2023). "Decorin and biglycan, two members of the SLRPs family, are associated with the initiation and progression of osteoarthritis, as both are upregulated." (PMID 36342580, 2023). "Notably, at the late stage of osteoarthritis, soluble fragments of biglycan are released to the synovial fluid and facilitate the loss of sulfated GAGs via the activation of NF-κΒ." (PMID 36342580, 2023). "Furthermore, in vitro studies on the progression of post-traumatic osteoarthritis indicate that decorin plays a more important role than biglycan in regulating cartilage degeneration, and biglycan is more important for regulating subchondral bone structure." (PMID 41465591, 2025). "Degradation of biglycan may contribute to ECM remodeling–related diseases such as osteoarthritis, rheumatoid arthritis, and IDD." (PMID 39951526, 2025). "According to a biglycan and fibromodulin double-deficient mouse model, osteoarthritis-related cartilage and bony defects in the TMJ were not identified until the age of 9 months although some histological changes in the condylar cartilage were found amongst 3-month-olds." (PMID 22003394, 2011). "For instance, the biglycan neoepitope BGN262 (the cleavage site is 262GLGHNQIRM) was shown to have a distinct cytoplasmic and intranuclear staining location in osteoarthritic subchondral bone sclerosis and this intracellular expression was more pronounced in osteoarthritis with increasing severity." (PMID 39951526, 2025).
lung cancer (8 papers, 2016 to 2023). A malignant neoplasm involving the lung. "In this study, we analyzed the association between BGN expression in TECs in lung cancer and cancer progression in patients." (PMID 33709550, 2021). "We showed the association between BGN levels in preoperative serum and clinicopathological parameters in 46 lung cancer patients." (PMID 33709550, 2021). "We showed that both BGN expression in TECs and BGN levels in patient serum were significantly associated with histology and T classification in lung cancer." (PMID 33709550, 2021). "Our study showed that BGN is expressed in TECs and that BGN expression in TECs is associated with tumor progression and prognosis in lung cancer." (PMID 33709550, 2021). "We also found that high BGN expression in TECs of lung cancer was significantly associated with shorter relapse‐free survival, shorter overall survival, and tumor progression in univariate analyses." (PMID 33709550, 2021). "Moreover, studies have shown that high expression of BGN is associated with reduced overall survival in lung cancer." (PMID 36523769, 2022). "BGN levels in preoperative serum of 46 patients with lung cancer was significantly correlated with BGN expression in the TECs." (PMID 33709550, 2021). "After analyzing the possibility of BGN expression in the tumor as a prognostic factor for patients with lung cancer, we found that BGN levels in preoperative sera of 46 patients with lung cancer was correlated significantly with BGN expression in tumors." (PMID 33709550, 2021). "We found that biglycan (BGN) is expressed in tumor endothelial cells (TECs) and that BGN expression in TECs is associated with tumor progression and prognosis in lung cancer." (PMID 33709550, 2021). "In this study, we analyzed the correlation between BGN expression in TECs in lung cancer, serum BGN levels, and cancer progression to evaluate the potential of BGN to serve as a biomarker." (PMID 33709550, 2021). "Second, we measured the BGN levels in preoperative serum of other 46 patients with lung cancer by ELISA, and analyzed the correlation between BGN expression in tumor tissues and blood BGN levels." (PMID 33709550, 2021). "Serum biglycan might be used as a non-invasive marker of liver fibrosis and also can be a potential biomarker for lung cancer." (PMID 36631795, 2023). "This suggests that BGN levels in preoperative serum may be a prognostic factor for patients with lung cancer." (PMID 33709550, 2021). "In addition, we searched the database to analyze the relationship between BGN expression and prognosis in lung cancer." (PMID 33709550, 2021). "As far as we are aware, our study is the first to show that BGN is a biomarker for lung cancer." (PMID 33709550, 2021). "Furthermore, BGN levels in the preoperative serum of patients with lung cancer correlates closely with BGN expression in TECs." (PMID 33709550, 2021). "No reports have been published on an association between BGN expression in tumor tissue and that in patient blood, but these reports encouraged us to analyze the expression and localization of BGN in tumor tissue and that in patient blood of lung cancer." (PMID 33709550, 2021). "However, because an operation was not usually indicated in cases of lung cancer with metastatic diseases, we could not demonstrate an association between BGN expression and metastasis." (PMID 33709550, 2021). "In this study, we confirmed that not only tumor blood vessels but also fibrotic tissues were BGN‐positive and tumor cells were BGN‐negative in the tumor part of lung cancer tissues." (PMID 33709550, 2021).
asthma (7 papers, 2006 to 2023). "Other abnormalities in airway matrix structure in asthma, include a specific increase in the lumican and biglycan isoforms, which is also associated with tissue injury and worsening of the lung function (FEV1 ≤ 80% predicted)." (PMID 30979017, 2019). "Percentage area of biglycan was significantly higher in both central airways and alveolar parenchyma of patients with uncontrolled compared to controlled asthma." (PMID 24950767, 2014). "This location is also abundant in fibroblasts and myofibroblasts in the asthma patient, while the proteoglycans, versican, biglycan, and decorin, accumulate in the submucosa below the epithelium in bronchial biopsies from asthma patients." (PMID 21658209, 2011). "In postmortem lung tissue from patients dying with fatal asthma, hyaluronan, versican, biglycan and decorin were prominently localized in the airway wall." (PMID 16643666, 2006). "Additionally, there were increases in the number of cells positive for ROCK1, ROCK2, TGF-β, MMP-9, MMP-12, and TIMP-1, and the percentages of isoprostane, biglycan, decorin, fibronectin, and collagen fibers, in the asthma group." (PMID 30979017, 2019). "Lung ECM remodeling in asthma is determined by the rate of ongoing deposition and degradation of proteins, including collagens I, III, and V, fibronectin, tenascin, lumican, and biglycan." (PMID 30979017, 2019).
liver fibrosis (7 papers, 2013 to 2026). "In conclusion, our findings uncover a novel mechanism whereby SPD ameliorates LSECs dysfunction and suppresses fibrosis progression by modulating LSECs-derived BGN, suggesting a new therapeutic strategy for liver fibrosis.Schematic working model of the study." (PMID 42098063, 2026). "Proteomic analyses of the ECM of liver biopsies of chronic hepatitis C patients with liver fibrosis revealed a downregulation of the ECM-bound form of biglycan." (PMID 34065048, 2021). "Animal models of liver fibrosis were chosen to investigate the relation between this novel biglycan marker and ECMR in fibrosis-related diseases." (PMID 23635022, 2013). "Examples were represented by elastin fragments in the serum of fibrotic and cirrhotic patients, the correlation of LAM-P1 serum level with the degree of fibrosis progression and inflammation in ALD and NAFLD patients, and the high levels of biglycan in the serum of rat models of liver fibrosis." (PMID 33262757, 2020). "The scope of the present study was to develop a novel enzyme-linked immunosorbent assay (ELISA) for the measurement of a MMP-9 and MMP-12-generated biglycan neo-epitope and to test its biological validity in a rat model of RA and in two rat models of liver fibrosis, chosen as models of ECMR." (PMID 23635022, 2013). "Considering that GP73 could act as an indicator for both liver necroinflammation and liver fibrosis, other serum biomarkers such as biglycan, which is closely correlated with both liver necroinflammation and fibrosis, probably could be used as a noninvasive necroinflammation marker in NASH." (PMID 32089754, 2020). "MMP-9 and MMP-12 are capable of degrading the ECM and generate specific biglycan-derived fragments that have been studied as biomarkers in liver fibrosis as they correlated with the severity of fibrosis, indicating that biglycan could mediate activation of sterile inflammatory responses." (PMID 33262757, 2020). "The proteoglycan biglycan (BGN) is involved in collagen fibril assembly and its fragmentation is likely to be associated with collagen turnover during the pathogenesis of diseases which involve dysregulated extracellular matrix remodeling (ECMR), such as rheumatoid arthritis (RA) and liver fibrosis." (PMID 23635022, 2013). "Serum BGN may be a new non-invasive indicative marker for the presence of non-alcoholic steato hepatitis (NASH) and liver fibrosis." (PMID 36631795, 2023). "As a biglycan, decorin is able to modulate TLR2- and TLR4-mediated signaling and play a role in inflammation; however, our knowledge about decorin and (HCV-induced) liver fibrosis remains piecemeal." (PMID 34065048, 2021).
Obesity (7 papers, 2012 to 2024). Accumulation of substantial excess body fat. "Collectively, studies show that elevated BGN expression and shedding was associated with obesity associated co-morbidities, rendering BGN as a potential diagnostic marker and therapeutic target." (PMID 32508807, 2020). "Biglycan upregulation in adipose tissues may be involved in insulin resistance associated with obesity." (PMID 27465988, 2016). "In addition to an intimate association with obesity, the biglycan mRNA level in each fat depot strongly and positively correlated with the expression of genes related to inflammation and ER stress, which are increased in obese adipose tissues." (PMID 27465988, 2016). "Furthermore, increased expression of biglycan was associated with impaired glucose tolerance and obesity in P. obesus, and we recently reported improved glucose tolerance in biglycan knockout mice on HFD relative to controls, implicating a possible role for biglycan in glucose metabolism." (PMID 23189205, 2012). "We recently also have demonstrated that biglycan is the principal proteoglycan synthesized and secreted by adipose tissue macrophages in obesity." (PMID 32970631, 2020). "We subsequently have shown that versican derived from adipocytes and biglycan derived from adipose tissue macrophages were increased in obesity." (PMID 32970631, 2020). "The present study was undertaken to determine the pattern and regulatory properties of biglycan expression in human adipose tissues in the context of obesity and its related diseases." (PMID 27465988, 2016). "In the present study, we characterized biglycan expression in various adipose depots in wild-type mice fed a low fat diet (LFD) or obesity-inducing high fat diet (HFD)." (PMID 23189205, 2012). "The lack of BGN expression in this HFD-fed model was associated with a reduction in obesity-driven inflammation in visceral AT independent of changes in adiposity." (PMID 32508807, 2020). "Although this work and our earlier report clearly shows that obesity or HFD induces the expression of biglycan in AT, the possible implication of inflammatory state in the regulation of biglycan expression is unknown." (PMID 22533381, 2012). "At present it is still unknown whether biglycan contributes to adipose tissue dysfunction in obesity." (PMID 23189205, 2012). "This suggests that biglycan could be involved in the development of AT inflammation and metabolic dysregulation in obesity." (PMID 22533381, 2012). "In summary, our findings show an increase in biglycan expression in adipose tissue during obesity." (PMID 23189205, 2012). "Furthermore, to understand how biglycan expression is induced upon obesity, we incubated human preadipocytes as well as differentiated adipocytes in a series of culture environments that could mimic the conditions during obesity." (PMID 27465988, 2016). "In an effort to explain the elevated biglycan mRNA in obese adipose tissues, we incubated human preadipocytes as well as fully differentiated human adipocytes in a series of culture environments that could mimic the conditions during obesity." (PMID 27465988, 2016). "We also showed that adipose tissue macrophages mainly synthesize and secrete biglycan, a proteoglycan found in the ECM in obesity." (PMID 32970631, 2020). "Biglycan, a small leucine rich proteoglycan ECM protein, is up-regulated in obesity and has recently been recognized as a pro-inflammatory molecule." (PMID 23189205, 2012). "It therefore appears that obesity, but not hyperglycemia, is a major factor in increasing biglycan mRNA in adipose tissues." (PMID 27465988, 2016). "To investigate the pattern and regulatory properties of biglycan expression in human adipose tissues in the context of obesity and its related diseases, we recruited 21 non-diabetic obese women, 11 type 2 diabetic obese women, and 59 normal-weight women." (PMID 27465988, 2016).
Obesity (continued). "Given that biglycan is released from the ECM under conditions of tissue stress and that unsequestered biglycan is an endogenous ligand for TLR2/4, the relevance of the current findings to the pathogenesis of obesity-related disorders such as insulin resistance warrant further studies." (PMID 27465988, 2016). "Accordingly, in obesity, it is tempting to speculate that the accelerated proteolytic release of sequestered biglycan from the ECM in turn stimulates gene transcription to replace the depleted biglycan, thereby creating the discrepancy between biglycan protein and mRNA levels in adipose tissue." (PMID 27465988, 2016).
rheumatoid arthritis (7 papers, 2013 to 2022). A chronic, systemic autoimmune disorder characterized by inflammation in the synovial membranes and articular surfaces. "Extensive degradation of both large and small PGs, such as decorin and biglycan were found in cartilages of patients suffering from OA and rheumatoid arthritis (RA)." (PMID 32353084, 2020). "Indeed, the biglycan fragments were increased in ex vivo degraded cartilage explants and in the serum of a rheumatoid arthritis (RA) rat model." (PMID 31947880, 2020). "High levels of soluble forms of BGN and DCN were found in synovial fluid of OA or rheumatoid arthritis patients." (PMID 32466468, 2020). "In rheumatoid arthritis (RA), autoantibodies targeting several innate immune cell ligands including citrullinated histones, fibrinogen, and biglycan have provided insights into the earliest autoantigen targets and potential mechanisms responsible for the onset and development of RA autoimmunity." (PMID 24877157, 2014).
tendinopathy (7 papers, 2012 to 2023). "Also, upregulation of genes encoding proteoglycans (BGN) glycoproteins (TNC, FN1, SPARC), integrins (ITGB1), and growth factors has been reported in tendinopathy patients." (PMID 38001919, 2023). "However, MMP1, MMP13, MMP10, ADAMTS5, TIMP3, versican, aggrecan, biglycan, decorin, fibronectin, fibrillin and COMP showed an opposite response with strain compared to tendinopathy." (PMID 23830915, 2013). "BGN and TNC were upregulated in tendinopathy, while DCN showed no change." (PMID 35008516, 2021).
Osteopenia (6 papers, 2010 to 2021). Osteopenia is a term to define bone density that is not normal but also not as low as osteoporosis. "In contrast, loss of biglycan leads to osteopenia and cortical thinning quite similar to GorabPrx1 and GorabRunx2 mutants." (PMID 29561836, 2018). "Human biglycan loss-of-function mutations cause aortic dilatation, malar hypoplasia, and osteopenia with thin cortices, a clinical picture somewhat reminiscent of GO." (PMID 29561836, 2018). "Interestingly, biglycan-deficient mice develop age-associated osteopenia thought to arise from defects in the maintenance and metabolic activity of osteogenic precursor cells." (PMID 20098702, 2010). "Biglycan binds various growth factors to modulate cell signaling pathways, and disruption of the biglycan gene results in osteopenia with decreased growth and bone mass." (PMID 32903857, 2020).
Sepsis (6 papers, 2019 to 2022). Sepsis is defined as life-threatening organ dysfunction caused by a dysregulated host response to infection. "Studies based on biglycan knock-out (Bgn-/0) mice found that biglycan deficiency in the lung, a major target organ in sepsis, resulted in attenuation of IL-1β mRNA expression, reducing the inflammatory response." (PMID 32878118, 2020). "The soluble form of biglycan initiates and perpetuates the inflammatory response by activating TLR2 and TLR4, and biglycan-deficient mice are less susceptible to death caused by TLR2- or TLR4-dependent sepsis." (PMID 32194548, 2020). "In addition, it was reported that biglycan-deficient mice show improved survival in LPS-induced sepsis and less severe inflammation in both models of sterile inflammatory renal injury and LPS-induced sepsis because of decreased levels of active caspase-1 and mature IL-1." (PMID 31739592, 2019). "Since platelets express TLR4 and bind to neutrophils in the capillaries of lung and liver upon sepsis, it is tempting to speculate that soluble biglycan is able to bind to platelet TLR4 to mediate platelet-induced inflammatory responses." (PMID 34830059, 2021).
Duchenne muscular dystrophy (5 papers, 2012 to 2023). Duchenne muscular dystrophy (DMD) is a neuromuscular disease characterized by rapidly progressive muscle weakness and wasting due to degeneration of skeletal, smooth and cardiac muscle. "We also showed that protein-anchoring therapy of biglycan ameliorated a mouse model of Duchenne muscular dystrophy." (PMID 33671084, 2021). "For instance, the small-leucine rich proteoglycan biglycan regulates the expression of utrophin in myotubes as well as in murine sarcolemma, and systemic delivery of recombinant human biglycan decreased fibrosis in a murine model (mdx model) of Duchenne muscular dystrophy." (PMID 37036009, 2023). "Indeed, biglycan is currently under investigation as a therapy for Duchenne muscular dystrophy." (PMID 37036009, 2023).
Ehlers-Danlos syndrome (5 papers, 2007 to 2019). The Ehlers–Danlos syndromes (EDS) are a clinically and genetically heterogeneous group of heritable connective tissue disorders (HCTDs) characterized by joint hypermobility, skin hyperextensibility, and tissue fragility. "Mice deficient in biglycan display a mild muscular dystrophy, and, along with mice deficient in decorin, are models of Ehlers-Danlos Syndrome, a connective tissue anomaly associated with uterine rupture." (PMID 22253749, 2012). "As a variant of Ehlers-Danlos Syndrome is caused by a genetic mutation resulting in abnormal biglycan and decorin secretion, we hypothesized that biglycan and decorin play a role in uterine function." (PMID 22253749, 2012). "Another study showed that DCN and BGN double-knockout (KO) mice directly resemble the rare progeroid variant of human Ehlers-Danlos syndrome (EDS), in which skin fragility and progeroid changes in the skin (reduced hypodermis) are dramatically displayed." (PMID 32063855, 2019).